LGALS3 (galectin 3)
Diseases named in the same sentence as LGALS3 in open-access papers (continued):
Sharing a sentence is not in itself a finding about the gene and the disease.
follicular adenoma (14 papers, 2003 to 2021). "Galectin 3 have been found to have higher immunoreactivity in papillary (also follicular variant) carcinoma compared to follicular adenoma, which is comparable to our results." (PMID 26503236, 2015). "In the present study Galectin-3 helped in the preoperative diagnosis of 100% (23/23) follicular adenomas on FNAC." (PMID 28811803, 2017). "Few studies, including the current, found difference in expression of Galectin 3 between follicular carcinoma and follicular adenoma." (PMID 26503236, 2015). "Some authors consider true galectin-3-positive follicular adenoma as an indication of potentially early or incipient carcinoma, in which the capsular and/or vascular invasion can not be histologically observed yet." (PMID 20181018, 2010). "Follicular adenomas showed intermediate expression of all markers between HN and malignant tumors ranging from 28.5% for galectin-3 to 57.1% for Ret." (PMID 19826479, 2009). "Galectin-3 expression was also detected in three out of six histologically confirmed follicular adenomas." (PMID 16804521, 2006). "The two undeterminate galectin-3 positive samples, which were diagnosed as benign, that is one follicular adenoma and one oncocytic adenoma, exhibited positivity in 30 and 20% cells, respectively." (PMID 16251880, 2005). "Regarding the detection of some galectin-3-positive follicular adenomas, we previously reported that these lesions may likely represent early follicular carcinomas, in which capsular and/or vascular invasion cannot be demonstrated yet." (PMID 16804521, 2006). "In this study, we detected three galectin-3-positive follicular adenomas out of 19 tested." (PMID 16804521, 2006). "However, most authors agree that the most significant localisation of galectin-3 in thyroid lesions is cytoplasm as nuclear staining can be observed in a high number of benign lesions namely follicular adenoma." (PMID 16251880, 2005). "Among the tested genes, the expression of SLC5A5 and LGALS3 were validated in a larger number of patients (n = 64) and our results show that SLC5A5 expression differentiated follicular adenomas from follicular carcinomas (area under the curve (AUC) = 0.831)." (PMID 30781659, 2019). "Statistically significant difference in expression of Galectin-3 and CD56 between follicular carcinoma and follicular adenoma was registered (p = 0.043; p = 0.028, respectively)." (PMID 26503236, 2015). "In our study, Galectin-3 was 100% negative in follicular adenomas because all 23 cases were not reactive on staining with this antibody." (PMID 28811803, 2017). "Interestingly, Galectin-3 and CD56 made statistically significant difference between follicular carcinoma and follicular adenoma." (PMID 26503236, 2015). "There was significant difference in CK19 and Galectin-3 expression between nodular goiter (or follicular adenoma) and PTC with lymphatic metastasis (or PTC without lymphatic metastasis), P < 0.05." (PMID 22188859, 2011). "Among the 34 galectin-3-negative microfollicular/solid lesions, 13 were histologically classified as follicular adenomas (39.3%), 20 as nodular hyperplasias (58.8%) and one as follicular carcinoma." (PMID 16804521, 2006). "Galectin-3 was negative in 100% (23/23) cases of follicular adenomas." (PMID 28811803, 2017). "However, he also demonstrated that a large proportion of follicular adenomas (72%) and multinodular goitres (57%) also expressed galectin-3 and its expression was no greater in follicular carcinomas than in follicular adenomas." (PMID 23658855, 2010). "Author MPP reviewed all cases of follicular adenomas and all pathological diagnoses remained the same, based on negative immunohistochemistry stains for HBME-1, Galectin-3 and CK19." (PMID 31898554, 2020). "Positive immunostaining of these markers especially galectin-3 and HBME-1 would be further in support of a follicular carcinoma rather than follicular adenoma." (PMID 19826479, 2009).
follicular carcinomas (14 papers, 2003 to 2021). "The expression of HBME-1 and galectin-3 among nine cases of follicular carcinoma was four out of nine cases (p<0.05) and six out of nine cases (p<0.05), respectively." (PMID 34934597, 2021). "The follicular thyroid carcinomas also demonstrated the positive expression of Galectin-3 by immunohistochemistry but much less as compared to PTC." (PMID 28811803, 2017). "A recent study showed the usefulness of immunohistochemical study of galectin-3 for the diagnosis of thyroid follicular carcinoma." (PMID 15083192, 2004). "However, data from us and other laboratories show that galectin-3 test method works well also in follicular carcinomas." (PMID 16804521, 2006). "Keeping in view the fact that two cases of follicular carcinoma (FC) had nuclear features of PTC, the expression of HBME-1 and galectin-3 was revised to two out of seven and four out of seven cases, respectively." (PMID 34934597, 2021). "One work showed the significant association between PTTG1 and Ki-67 in pituitary adenomas, while the other studied the combination of Ki-67, Galectin-3, and PTTG to distinguish malignant forms of papillary or follicular thyroid cancer." (PMID 30911297, 2019). "Galectin-3 could not distinct papillary from follicular carcinoma." (PMID 26503236, 2015).
glaucoma (14 papers, 2021 to 2025). Increased pressure in the eyeball due to obstruction of the outflow of aqueous humor. "Lgals3, which encodes a member of beta-galactoside binding lectin family, Gal-3, was found to be upregulated in retinal microglia in an inducible rodent glaucoma study in addition to DBA/2J dLGN in the current study." (PMID 40373024, 2025). "Galectin-3 deficiency was shown to be neuroprotective in glaucoma, such that genetic or pharmacologic targeting of Galectin-3 conferred robust protection of RGCs despite IOP elevation." (PMID 36779012, 2023). "Conversely, the presence of the ε3 isoform and overall APOE gene expression (APOE+/+) may increase the risk of RGC death in glaucoma by promoting microglial phenotypic changes and upregulating galectin-3." (PMID 38674156, 2024). "Animal experiments suggest that APOE gene deletion (APOE−/−) and the ε4 isoform may reduce the risk of RGC loss in glaucoma by inhibiting kainic acid receptor signaling, modulating microglial activation, and reducing galectin-3 expression." (PMID 38674156, 2024). "Collectively, these findings support the involvement of LGALS3 in mediating pathological inflammation and phagocytic responses of microglia in glaucoma neurodegeneration." (PMID 41306973, 2025). "In the microbead model of glaucoma, Lgals3 is one of the genes most strongly affected by APOE deficiency." (PMID 41306973, 2025). "So far, in vivo and in vitro studies indicated that Lgals3/galectin-3 plays critical roles in several ocular diseases, e.g., dry eye, glaucoma, uveitis, and diabetic retinopathy." (PMID 39595213, 2024). "Taken together, these studies support a role for Galectin-3 in pathological inflammation and efferocytosis of neurons in glaucoma." (PMID 36779012, 2023). "Indeed, one of the most highly up-regulated molecules downstream of ApoE signaling in glaucoma was Galectin-3, a secreted carbohydrate binding lectin previously implicated in a myriad of CNS degenerations." (PMID 36779012, 2023). "Finally, upregulation of galectin-3 is also found in an activated microglia state associated with neurodegeneration and may act to propagate the activated state to nearby microglia; moreover, recent work has shown that disrupting its expression is protective in a mouse model of glaucoma." (PMID 37829657, 2023). "The increase in a marker of phagocytic capacity (galectin-3) combined with accumulation of degradation-bound mitochondria, although superficially paradoxical, may aid in identifying the contributions of phagocytic and mitochondrial dysfunction in glaucoma." (PMID 37829657, 2023). "Thus, we should consider the possibility that astrocytic upregulation of galectin-3 potentiates the microglial and/or peripheral immune response in glaucoma, which may contribute to a neuroinflammation in the region." (PMID 37829657, 2023). "Elevated Galectin-3 has recently been detected in multiple animal models of glaucoma and inhibiting Galectin-3 using an intravitreal injection of TD139 (a Galectin-3 small molecule inhibitor) is neuroprotective." (PMID 39574161, 2024). "Additionally, sitagliptin inhibited the overexpression of galectin-3 and gamma-synuclein in ONH, two significant mediators of the neurodegenerative process in glaucoma." (PMID 41515932, 2025).
liver cancer (14 papers, 2011 to 2025). An epithelial or non-epithelial malignant neoplasm that arises from the liver. "In summary, seven of the genes (VEGFA, CTNNB1, SPP1, PPARG, RAC1, HSP90AA1, and LGALS3) were highly unregulated in patients with liver cancer." (PMID 35069936, 2022). "Previously it was reported that treatment of mouse primary hepatocytes with peroxisomes proliferators (including Wy14643) for 24 hours led to upregulation of 11 genes related to liver cancer (i.e. Angptl4, Bnip3, Dbi, Fabp1, Fabp2, Fasn, HifIa, Lgals3, Ly6d, Mgll, SerpineI)." (PMID 25511156, 2014). "Analysis of LGALS3 expression patterns in human MASLD and liver cancer datasets (GSE135251, GSE126848, GSE124535, GSE130970 and The Cancer Genome Atlas Liver Hepatocellular Carcinoma) revealed a significant up-regulation of LGALS3 levels in MASH compared to healthy or MASLD tissues." (PMID 40608687, 2025).
osteoarthritis (14 papers, 2006 to 2026). A noninflammatory degenerative joint disease occurring chiefly in older persons, characterized by degeneration of the articular cartilage, hypertrophy of bone at the margins and changes in the synovial membrane. "Galectin-3 (Gal-3), a member of the β-galactoside-binding protein family, is critically involved in inflammation, extracellular matrix remodelling, and cartilage degeneration in osteoarthritis (OA)." (PMID 42086698, 2026). "Having previously identified homodimeric galectin-1 and chimera-type galectin-3 as molecular switches in osteoarthritis progression, we here provide proof-of-principle evidence for an intra-network cooperation of galectins with three types of modular architecture." (PMID 29934665, 2018). "Interestingly, Galectin-3 and its binding protein, but not Galectin-1, were reported to be elevated in RA but not in osteoarthritis." (PMID 16507131, 2006).
renal cell carcinoma (14 papers, 2011 to 2025). "Galectin-3 is upregulated in human renal cell carcinoma and associated with higher expression levels of stemness-related genes, such as Oct4, Sox2, and Nanog." (PMID 36873388, 2023). "In renal cell carcinoma (RCC), galectin-3 expression rates are significantly elevated in the serum and tumor tissues of patients with renal cell carcinoma." (PMID 40426926, 2025). "Renal cell carcinoma RCC FG1 cells were used to search for nuclear interaction partners of galectin-3." (PMID 27435226, 2016). "High levels of galectin-3 in renal cell carcinomas was found in primary and metastatic renal cell carcinomas; metastatic carcinomas had higher levels than primary carcinomas suggesting a role in progression." (PMID 22039439, 2011). "For renal cell carcinoma a putative involvement of galectin-3 in this pathway is evidenced by reduced β-catenin levels detected in this as well as in prior studies." (PMID 21958686, 2011). "In renal cell carcinoma, downregulation of galectin-3 could strongly inhibit cancer cell invasion, colony formation, sphere-forming ability and stemness-associated gene expression." (PMID 36873388, 2023). "On the contrary, clear cell RCC stains positive for a variety of markers such as vimentin, galectin-3, CD10, CAIX, renal cell carcinoma (RCC), PAX-8, and epithelial membrane antigen (EMA)." (PMID 37990226, 2023).
Arthritis (13 papers, 2006 to 2024). Inflammation of a joint. "The joint inflammation and bone erosion of antigen-induced arthritis were markedly suppressed in galectin-3-deficient mice as compared with the wild type mice." (PMID 24416634, 2013). "Recent studies with galectin-3-deficient mice further confirmed the stimulating role of galectin-3 in arthritis." (PMID 24416634, 2013). "The reduced arthritis in galectin-3-deficient mice was accompanied by decreased levels of antigen-specific IgG and proinflammatory cytokines including TNFα, IL-6, and IL-17." (PMID 24416634, 2013). "Genes known to be involved in autoimmune response and arthritis, such as those encoding Galectin-3, Versican, and Socs3, were identified and validated by quantitative TaqMan RT-PCR analysis using independent blood samples." (PMID 16507131, 2006). "Furthermore, an exogenous supply of recombinant galectin-3 restored the reduced arthritis and cytokine production in galectin-3-deficient mice." (PMID 24416634, 2013). "Studies have shown that Galectin-3 can induce and regulate the secretion of inflammatory factors, and then participate in the generation and development of arthritis." (PMID 38561725, 2024). "Studies indicate that galectin-3 has a role in driving RA pathogenesis as indicated by reduced severity of arthritis in galectin-3 knockout mice and induction of pro-inflammatory cytokine secretion by synovial fibroblasts." (PMID 33924323, 2021). "For example, galectin-1 knockout (KO) mice develop earlier onset and more severe collagen-induced arthritis, and galectin-3 KO mice have reduced inflammation and bone erosion in response to antigen-induced arthritis as compared to wild-type mice." (PMID 30525048, 2018). "On the other hand, exogenous intra-articular galectin-3 administration promoted the development of arthritis in mice, and inhibition of galectin-3 through lentiviral-mediated delivery of galectin-3 shRNA ameliorated collagen-induced arthritis in rats." (PMID 30525048, 2018). "Receiver operating characteristic (ROC) curve analysis was carried out to assess the discriminant capacity of galectin-3 against arthritis subsets." (PMID 28446218, 2017). "Synovial inflammation and structural joint damage was lower in galectin-3–/– mice with antigen-induced arthritis as compared with wild-type controls." (PMID 28446218, 2017). "This study provided the direct evidence that galectin-3 plays a crucial role in the development of arthritis in animal models." (PMID 24416634, 2013). "However, the link between galectin-3 and OA is less clear and, to our knowledge, no human studies have documented elevations in synovial fluid galectin-3 levels preceding the development of arthritis." (PMID 30525048, 2018). "Together, our results suggest that galectin-3 reinforces the lubricin boundary layer; which, in turn, enhances cartilage lubrication and may delay the onset and progression of arthritis." (PMID 27157803, 2016). "Because lubricin and galectin-3 interact in a carbohydrate-dependent manner, glycosylation changes in arthritis may have significant effects on galectin-3 stabilization of the lubricin boundary layer." (PMID 27157803, 2016). "Studies with CIA rats found increased galectin-3 secretion into the plasma over time, which correlated with the disease progression, implicating that galectin-3 promotes the development of experimental arthritis." (PMID 24416634, 2013). "In animal models, galectin-3 aggravates antigen-induced arthritis." (PMID 24416634, 2013).
breast tumor (13 papers, 2010 to 2024). "It was recently demonstrated that galectin-3 is a surrogate diagnostic marker for MMP activity in growing breast tumor." (PMID 23658855, 2010). "Our previous studies have shown that primary breast tumors were more aggressive and had a greater potential to metastasize to the bone marrow when injected subcutaneously in Galectin-3 knockout (Lgals3−/−) mice." (PMID 31949431, 2019). "In a xenograft model, galectin-3 was shown to be upregulated in breast tumor cells proximal to the stroma." (PMID 24982845, 2014). "Nevertheless, the survival analysis disclosed no prognostic correlation to either cytoplasmic or nuclear localization of galectin-3 on breast tumor cells." (PMID 24982845, 2014). "More recently, absence of Galectin-3 (Gal-3), a glycan-binding lectin, has been associated with higher in vivo growth in murine breast tumors and poor prognosis in node-positive breast cancers." (PMID 32231800, 2020). "Moreover, it appears that LGALS3 expression is lower at metastatic sites compared to primary breast tumors." (PMID 27687248, 2016). "We also used two galectin-transfected cell lines derived from the galectin-3 negative human breast tumor cell line SKBR3." (PMID 28986561, 2017).
endometriosis (13 papers, 2013 to 2025). The growth of functional endometrial tissue in anatomic sites outside the uterine body. "It was found that both galectin-3 deficiency and Gal3C presence impaired endometriosis development, and there was a significant reduction in both the lesion implantation and size." (PMID 32033052, 2020). "This study aimed to assess Galectin-3 (Gal-3) levels in the serum of patients with endometriosis compared to asymptomatic controls and investigate serum Gal-3 level changes over a one-year follow-up period of patients with endometriosis." (PMID 40004091, 2025). "Analogically to galectin-1, galectin-3 expression was enhanced in endometriosis and eutopic endometrium of endometriosis patients." (PMID 36612107, 2022). "This study indicates a possibly significant role of galectin-3 in endometriosis development and highlights the potential therapeutic approach of galectin-3 inhibition in the treatment of endometriosis." (PMID 32033052, 2020). "Importance of galectin-3 overexpression in the development of endometriotic lesions and the effect of recombinant galectin-3 carbohydrate recognition domain Gal3C in an experimental endometriosis treatment were demonstrated." (PMID 32033052, 2020). "The pro- and anti-apoptotic properties of galectin-3 may serve as a possible explanation for the increase in galectin-3 concentration in the PF of women with endometriosis." (PMID 32033052, 2020). "This study suggests that galectin-3 also may play a role in the development and/or progression of endometriosis." (PMID 32033052, 2020). "Furthermore, galectin-3 expression has been observed to be higher in endometriosis than in the eutopic endometrium, indicating that galectin-3 has a potential role in the development of endometriosis and subsequently, in CCC." (PMID 24179489, 2013). "It is also worth noting that these inhibitors have not been tested in tumors associated with endometriosis, but studies suggest that galectin inhibitors could be effective against these forms of cancer if they overexpress galectin-1 or galectin-3." (PMID 32033052, 2020). "Expression of galectin-3 was investigated using immunohistochemistry (IHC) in both patients with endometriosis and negative controls." (PMID 32033052, 2020). "Complete inhibition of galectin-3 or the delivery of Gal3C may lead to other downstream effects impacting or disrupting signaling cascades independent of endometriosis development." (PMID 32033052, 2020). "Furthermore, galectin-3 has been shown to interact with KRAS protein and contribute to cellular growth, proliferation, inflammation, and the uptake of nutrients in endometriotic lesions and may be involved in the maintenance and propagation of endometriosis." (PMID 32033052, 2020). "However, galectin-3 and ST2, a member of the interleukin (IL)-1 receptor family, had significantly higher concentrations in the peritoneal fluid (PF) of women with endometriosis compared to controls without endometriosis." (PMID 32033052, 2020).